SLC38A2 (solute carrier family 38 member 2)
Description:
Symporter that cotransports neutral amino acids and sodium ions from the extracellular to the intracellular side of the cell membrane. The transport is pH-sensitive, Li(+)-intolerant, electrogenic, driven by the Na(+) electrochemical gradient and cotransports of neutral amino acids and sodium ions with a stoichiometry of 1:1. May function in the transport of amino acids at the blood-brain barrier. May function in the transport of amino acids in the supply of maternal nutrients to the fetus through the placenta (By similarity). Maintains a key metabolic glutamine/glutamate balance underpinning retrograde signaling by dendritic release of the neurotransmitter glutamate (By similarity). Transports L-proline in differentiating osteoblasts for the efficient synthesis of proline-enriched proteins and provides proline essential for osteoblast differentiation and bone formation during bone development (By similarity).
Synonyms: ATA2; KIAA1382; SAT2; SNAT2; PRO1068
Tractability: Antibody: its Gene Ontology location is reachable by antibodies, with high confidence; UniProt places it where antibodies can reach, with medium confidence; UniProt predicts a signal peptide or a membrane-spanning region; the Human Protein Atlas places it where antibodies can reach. PROTAC: UniProt records ubiquitination sites on it; ubiquitination databases record sites on it.
Gene: Protein-coding gene on chromosome 12 (46,358,185 to 46,372,832, reverse strand). Ensembl gene ENSG00000134294.
Subcellular location: Cell membrane
Subcellular location (Human Protein Atlas): Plasma membrane
Pathways (Reactome):
Neuronal System: Glutamate Neurotransmitter Release Cycle
Transport of small molecules: Amino acid transport across the plasma membrane
Gene Ontology:
Molecular function: amino acid transmembrane transporter activity; amino acid:sodium symporter activity; neutral L-amino acid:sodium symporter activity; protein binding; acidic amino acid transmembrane transporter activity; alanine:sodium symporter activity; glycine:sodium symporter activity; L-asparagine:sodium symporter activity; L-glutamine transmembrane transporter activity; L-serine transmembrane transporter activity; proline:sodium symporter activity; neutral L-amino acid transmembrane transporter activity
Biological process: amino acid transmembrane transport; amino acid transport; cellular response to arsenite(3-); neutral amino acid transport; positive regulation of gene expression; positive regulation of RNA splicing; regulation of cellular response to stress; alanine transport; amino acid import; glutamine transport; L-glutamine import across plasma membrane; L-proline import across plasma membrane; L-serine import across plasma membrane; L-serine transport; neurotransmitter transport; proline transport; regulation of glutamate secretion, neurotransmission; transport across blood-brain barrier; acidic amino acid transport; asparagine transport; cellular response to amino acid starvation; cellular response to mechanical stimulus; cerebral cortex development; female pregnancy; glycine betaine transport; and 3 more
Cellular component: cytoplasm; plasma membrane; axon; brush border; dendrite; neuronal cell body; sarcolemma
Genetic constraint (gnomAD): Loss-of-function variants: 10 observed, 55.08 expected, observed/expected ratio (o/e) 0.18, 90% interval 0.11 to 0.31. The upper end of that interval is the gene's LOEUF score, 0.31, which puts it in group 1 of 6, group 1 being the genes least tolerant of losing a copy. Missense variants: 502 observed, 593.1 expected, observed/expected ratio (o/e) 0.85, 90% interval 0.79 to 0.91. Synonymous variants: 199 observed, 210.86 expected, observed/expected ratio (o/e) 0.94, 90% interval 0.84 to 1.06.
Homologues: Orthologues: chimpanzee SLC38A2 (99% identical), macaque SLC38A2 (97% identical), dog SLC38A2 (92% identical), guinea pig SLC38A2 (89% identical), rat Slc38a2 (88% identical), mouse Slc38a2 (88% identical), rabbit SLC38A2 (87% identical), tropical clawed frog slc38a2 (71% identical), pig SLC38A2 (71% identical), zebrafish slc38a2 (69% identical), Drosophila melanogaster CG32079 (17% identical), Drosophila melanogaster CG13384 (16% identical), and 15 more. Paralogues in human: SLC38A4 (62% identical), SLC38A3 (52% identical), SLC38A1 (49% identical), SLC38A5 (47% identical), SLC38A6 (41% identical), SLC38A10 (24% identical), SLC38A11 (21% identical), SLC38A7 (21% identical), SLC38A9 (20% identical), SLC36A4 (19% identical), SLC36A1 (19% identical), SLC36A2 (19% identical), and 3 more.
Diseases named in the same sentence as SLC38A2 in open-access papers:
SLC38A2 is named in the same sentence as 60 diseases in open-access papers, as found by Europe PMC text mining. Sharing a sentence is not in itself a finding about the gene and the disease. The quoted sentences say what the papers report.
breast carcinoma (28 papers, 2012 to 2026). "SLC38A2 has been identified as a highly expressed amino acid transporter in six breast cancer cell lines, and high levels of SLC38A2 are associated with poor clinical outcomes in TNBC patients." (PMID 39973065, 2025). "High expression of SLC38A2 protein was associated with poor breast cancer specific survival in a large cohort of patients (p = 0.004), particularly in TNBC (p = 0.02)." (PMID 33028955, 2021). "Regarding breast cancer metastatic sites, high SLC38A2 protein levels were associated with the development of distant metastases in the brain (p = 0.005) but not at other sites." (PMID 33028955, 2021). "High SLC38A2 expression is associated with poor clinical prognosis in breast cancer patients, including triple-negative breast cancer (TNBC)." (PMID 33401748, 2021). "Moreover, SLC38A2 expression was associated with poor BCSS in the entire cohort of breast cancer patients and particularly in TNBC (p = 0.02)." (PMID 33028955, 2021). "Paclitaxel-induced endoplasmic reticulum stress in breast cancer cells promotes ubiquitination and degradation of SLC38A2 by the ubiquitin ligase RNF5, leading to increased autophagy and cell death." (PMID 39973065, 2025). "Overexpression of SLC38A2 leads to complete resistance to anti-estrogen therapy and is induced in tamoxifen resistance, contributing to endocrine resistance in breast cancer." (PMID 39973065, 2025). "Knockdown of SLC38A2 in breast cancer cells regulates mTORC1 signaling, reduces glutamine consumption in breast cancer cell lines, sensitizes cells to low-glutamine conditions, and increases ROS production." (PMID 39973065, 2025). "As a glutamine transporter induced by oxygen deprivation in breast cancer, the upregulation of SLC38A2 results in resistance to hormone therapy and subsequently a poorer prognosis." (PMID 38459595, 2024). "Among those transporters, SLC38A2 or SNAT2 have been reported to be overexpressed in tumors including prostate cancer, breast cancer, pancreatic cancer, and colorectal cancer." (PMID 36874096, 2023). "Hypoxia induced HIF1α positively regulates SLC38A1 and SLC38A2 expression in adipose cells during obesity and in breast cancer cells, respectively." (PMID 36613847, 2022). "In conclusion, this study provides evidence for future investigation of SLC38A2 as a potential target for TNBC breast cancer patients and as a marker for sensitivity to Gln deprivation." (PMID 33028955, 2021). "SLC38A2 is induced by hypoxia and its expression is related to endocrine resistance in breast cancer." (PMID 34704597, 2021). "In contrast, the expression of SLC38A2 is reduced in primary breast cancer tissues compared with normal breast tissue." (PMID 34704597, 2021). "Two recent studies have reported that SLC38A2 plays a critical role in supplying glutamine to breast cancer cells." (PMID 34704597, 2021). "Our results showed that the anti-tumour effect of SLC38A2 blockade in breast cancer cell lines, particularly in the HCC1806 TNBC cell line, in low Gln medium is partially mediated by oxidative stress." (PMID 33028955, 2021). "To investigate the role of SLC38A2 in breast cancer growth, we grew spheroids from three Gln- sensitive cell lines (MCF7, MDA-MB-231 and HCC1806) in normal medium and low Gln medium." (PMID 33028955, 2021). "Slc38a1 and Slc38a2 are expressed at low levels in normal mammary tissue, and their expression is up-regulated in all three subclasses of breast cancer." (PMID 34704597, 2021). "The prognostic value of SLC38A2 in a cohort of breast cancer was determined by immunohistochemistry." (PMID 33028955, 2021). "To examine the role of SLC38A2 in breast cancer patients, we stained a TMA of 1,685 primary breast cancer samples." (PMID 33028955, 2021). "We found the Gln transporter SLC38A2/SNAT2 to have the highest expression level in many breast cancer cell lines." (PMID 33028955, 2021).
breast carcinoma (continued). "The role and localisation of the Gln transporter SLC38A2/SNAT2 in response to Gln deprivation or pharmacological stresses was examined in a panel of breast cancer cell lines." (PMID 33028955, 2021). "SLC38A2 was identified as a strongly expressed amino acid transporter in six breast cancer cell lines." (PMID 33028955, 2021). "RNF5 regulates the turnover of SLC1A5 and SLC38A2 in about 30% of breast cancer patients that are responsive to taxanes-based therapies, which is associated with better prognosis." (PMID 26425657, 2015). "In this case we would predict hypomethylation of the potential promoter region of SLC38A2 would result in higher expression of SLC38A2 in the breast cancer samples analyzed." (PMID 22936948, 2012). "Although this would require verification, SLC38A2 gene expression is found to be upregulated in various cell lines including ssMCF7 breast cancer and HMEC184 breast cancer." (PMID 22936948, 2012). "Furthermore, a distinct expression profile of SLC38A2 emerges across breast cancer subtypes when compared to normal tissue." (PMID 38459595, 2024). "Given that SLC38A5 as well as SLC38A2 might have relevance to breast cancer growth and progression, we analyzed the expression of these two transporters in breast cancer using the TCGA (The Cancer Genome Atlas) database." (PMID 34704597, 2021). "We also confirmed a route for SLC38A2 degradation via autophagy in breast cancer cell lines." (PMID 33028955, 2021). "Similarly, SLC38A2 mRNA was also the most abundant transcript amongst a wide range of AAT in different breast cancer cell lines from the Cancer Cell Line Encyclopaedia (CCLE)." (PMID 33028955, 2021). "Besides, SLC38A2 expression is induced by hypoxia and estrogen receptor alpha (ERα) and contributes to the resistance to anti-endocrine therapy in breast cancer." (PMID 33401748, 2021). "Finally, our analysis of clinical data from a large breast cancer cohort suggests that high baseline SLC38A2 protein expression correlates with poor BCSS survival in patients with breast cancer and with TNBC." (PMID 33028955, 2021). "Despite the role of glutamine metabolism in promoting tumor progression being well documented, the potential roles of these transporters are less investigated particularly in terms of endocrine resistance in luminal breast cancer, apart from SLC38A2 and SLC7A5." (PMID 34282517, 2021). "Only recently, a couple of studies have focused on SLC38A2 in breast cancer." (PMID 34704597, 2021). "Overall, the level of the glutamine carrier proteins SLC1A5 and SLC38A2 was found to be excellent predictor of the outcome for breast cancer patients where a low level of these carrier proteins associates with a better outcome, including a better response to therapy." (PMID 26425657, 2015). "These diverse observations highlight potential variations in the involvement of SLC38A2 across different pathological subtypes of breast cancer and at various treatment stages, underscoring the need to consider the heterogeneity when targeting SLC38A2 for therapeutic interventions in breast cancer." (PMID 38459595, 2024). "Collectively, our data suggest that hSPAR can downregulate SLC38A2 expression, deprive cellular glutamine level, and trigger P27KIP1’s lysosomal translocation in breast cancer cells." (PMID 39875724, 2025). "Breast cancer cell-secreted miR-199b-5p targets SLC1A2 in astrocytes and SLC38A2 and SLC16A7 in neurons, hijacking neuron-astrocyte metabolic coupling." (PMID 39973065, 2025). "It has been demonstrated that SLC1A5, SLC6A14, SLC7A11, SLC3A1, SLC7A5, SLC38A2, and SLC38A5 are significantly expressed in breast cancer cells." (PMID 39973065, 2025). "It is suggested that the transporters of the neutral amino acid carrier family, sodium-coupled transporters in system A and system N, SLC38A2 and SLC38A5, are overactive in HER2-positive luminal B subtype breast cancer." (PMID 39852119, 2024).
breast carcinoma (continued). "The functional features of SLC38A2 will be described in more detail in the section on the adjacent expression of this transporter in TNBC and HER2-positive breast cancer." (PMID 39852119, 2024). "The increased activity of transmembrane transporters SLC1A5 and SLC38A2 was shown in TNBC and HER2-positive breast cancer." (PMID 39852119, 2024). "In breast cancer, RNF5 is involved in the degradation of glutamine transporters SLC1A5 and SLC38A2, which are aberrantly folded following chemotherapy-induced ER stress." (PMID 35406574, 2022). "In contrast to RNF5 pro-tumor activity, in breast cancer, RNF5 promoted ubiquitination and degradation of glutamine transporters SLC1A5 and SLC38A2, which were aberrantly folded following chemotherapy-induced ER stress." (PMID 35406574, 2022). "There have been two recent reports on the expression of SLC38A2, another member of the SLC38 family, in breast cancer." (PMID 34704597, 2021). "Similar to MDA-MB-231 cells, the effects of hSPAR on SLC38A2, P27KIP1, mTOR signaling, and cell proliferation were also observed in breast cancer MCF7 cells (Luminal-A subtype) (Fig. EV4I–L) and MDA-MB-468 cells (triple-negative subtype) (Fig. EV4E-H), but not in HEK293T cells (Fig. EV4A–D)." (PMID 39875724, 2025). "Notably, while SLC38A2 is downregulated in ductal breast carcinoma, an upregulation is observed in TNBC and hormone-resistant breast cancers." (PMID 38459595, 2024). "The functional features of SLC38A2 are described in the section on HER2-positive breast cancer and will not be discussed in detail here." (PMID 39852119, 2024). "SLC38A2 protein expression was observed, predominantly in the cytoplasm of invasive breast cancer cells, with expression levels varying from absent to high." (PMID 33028955, 2021). "As SLC38A2 was upregulated during different stresses and degraded by autophagy, we investigated if the expression of SLC38A2 correlated with ATF4 and autophagic markers in breast cancer patients." (PMID 33028955, 2021).
pancreatic cancer (13 papers, 2021 to 2025). "In particular, inhibition of SLC38A2 caused a metabolic crisis in pancreatic cancer cells and suppressed proliferation, suggesting the possibility of therapeutic intervention." (PMID 35370770, 2022). "It has been shown that pancreatic cancer cells upregulate SLC38A2 to increase alanine uptake to support their metabolism by replacing glucose and glutamine to fuel the TCA cycle." (PMID 37210563, 2023). "The blank intersection was discussed in this report and SLC38A2 was supported to be a tumor suppressor in pancreatic cancer as well." (PMID 37005877, 2023). "It was recently demonstrated that alanine uptake and utilization through the SLC38A2 membrane transporter played a key role in pancreatic cancer metabolism and proliferation." (PMID 34685601, 2021). "In pancreatic cancer, SLC38A2 represents the major AAT for alanine, which is then deaminated to pyruvate (which can maintain the tricarboxylic acid cycle) in the presence of pyruvate carboxylase." (PMID 33028955, 2021). "Additionally, we investigated the enrichment of SLC38A2 at the single-cell level in 12 types of cancer and analyzed its temporal expression patterns in different cell subgroups in breast and pancreatic cancer." (PMID 41040664, 2025). "This study attempts to investigate whether hsa_circRNA_001859 (circ_001859) could regulate the proliferation and invasion of pancreatic cancer through the miR-21-5p/SLC38A2 pathway." (PMID 37005877, 2023). "In addition, we used the TCGA database to analyze the relationship between SLC38A2 and pancreatic cancer prognosis and found that high expression of SLC38A2 was significantly correlated with poor prognosis (HR= 1.8, P= 0.01)." (PMID 37005877, 2023). "but the role of miR-21-5p and SLC38A2 in pancreatic cancer is still unclear." (PMID 37005877, 2023). "Taken all together, circ_001859 which was lowly expressed in pancreatic carcinoma could suppress the ability of proliferation, migration and invasion of pancreatic cancer cells by down-regulating miR-21-5pand up-regulating SLC38A2." (PMID 37005877, 2023). "Other studies have shown that SLC38A2 plays an important role in pancreatic cancer." (PMID 37005877, 2023). "Further, through bioinformatics and molecular biological verification, we found that circ_001859 might regulate the proliferation, metastasis and EMT proceedings of pancreatic cancer through the miR-21-5p/SLC38A2 pathway." (PMID 37005877, 2023). "This study suggests that circ_001859 may inhibit the proliferation, invasion and EMT of pancreatic cancer through the miR-21-5p/SLC38A2 pathway." (PMID 37005877, 2023). "Alanine uptake in pancreatic cancer cells is dependent on SLC38A2." (PMID 35370770, 2022). "Notably, SLC38A2/SNAT2 was identified to be the main concentrative alanine transporter utilized by pancreatic cancer cells and targeting SLC38A2 was sufficient to suppress alanine uptake by pancreatic cancer cells and cause significant re-wiring of compartmentalized pyruvate metabolism." (PMID 33669382, 2021). "It was demonstrated that pancreatic cancer cells and PSCs express SLC38A2 and SLC1A4 respectively to perform alanine exchange so as to meet the high alanine requirement of pancreatic cancer cells." (PMID 37033960, 2023). "Several downstream proteins have been discussed to be tumor regulator in pancreatic cancer, such as FBXO11, IL-6 and RBM3 except SLC38A2." (PMID 37005877, 2023). "In view of the fact that SLC38A2 and SLC1A4 compete for alanine in pancreatic cancer, we speculated whether SLC38A2, which is highly expressed in DCs, also has a similar phenomenon in the immune microenvironment to meet its function." (PMID 40688069, 2025). "Furthermore, targeting secondary glutamine transporters (e.g., SLC38A2, SLC6A14) genetically or pharmacologically (e.g., α-methyltryptophan) significantly suppresses amino acid homeostasis and tumor growth in pancreatic cancer." (PMID 33669382, 2021).
pancreatic cancer (continued). "However, deletion of SLC38A2 in pancreatic cancer failed to impact either BCAA or glutamine uptake flux despite significantly decreasing intracellular glutamine levels." (PMID 33669382, 2021).